VIM (vimentin)
Diseases named in the same sentence as VIM in open-access papers (continued):
Sharing a sentence is not in itself a finding about the gene and the disease.
oral cancer (continued). "It even reduced the phosphorylation of ERK1/2 and AKT1 with concomitant downregulation of cyclin D1 (CCND1), cadherin 2 (CDH2), and vimentin (VIM) and upregulation of cadherin 1 (CDH1) expression suggesting its anti-proliferative and anti-EMT effects in oral cancer." (PMID 36761830, 2022). "In conclusion, our findings suggest that overexpression of IL-6 and IL-8 promotes the EMT and invasion abilities of oral cancer cells through the STAT3 signaling pathway and also decreases E-cadherin expression and increases vimentin expression; these effects are abolished by chrysophanol." (PMID 34063134, 2021). "In research on human oral cancer cells, it was demonstrated that menadione reduced metastatic potential by expression induction of E-cadherin and down-regulation of EMT markers such as vimentin and fibronectin." (PMID 34400945, 2021). "In conclusion, our findings suggest that the overexpression of CA III promotes the EMT, migration, and invasion abilities of oral cancer cells through the FAK/Src signaling pathway and transcription factors Slug and Twist, as well as decreases E-cadherin expression and increases vimentin expression." (PMID 32183030, 2020). "Similarly, expression of genes involved in EMT as well as metastasis such as VIM, TWIST and MMP7 were reduced upon silencing of YY1 in qRT-PCR experiment, indicating a regulatory role of YY1 in metastasis and invasion of oral cancer." (PMID 31217904, 2019). "Likewise, in oral cancer samples, it has been shown that E-cadherin is downregulated in HPV-positive samples in comparison with HPV-negative ones, while, vimentin expression remained unaltered; herein, it is important to highlight that both E-cadherin and vimentin are important biomarkers of EMT." (PMID 29765906, 2018). "Since tissue availability in oral cancers and precancers involve invasive procedures as a biopsy, we wanted to evaluate if vimentin could be detected in saliva, as saliva can serve as a noninvasive medium for the early detection and also for disease monitoring." (PMID 35498535, 2022). "Moreover, RUEA extracts inhibited the expression of E-cadherin, vimentin, and Snail in Prx1 knockdown SCC15 cells for 48 h, indicating that RUEA extracts may target other molecules in addition to Prx1 to inhibit cell migration and invasion in oral cancer." (PMID 29218012, 2017).
nasopharyngeal carcinoma (34 papers, 2016 to 2025). A carcinoma arising from the nasopharyngeal epithelium. "MiR-10b is highly expressed in nasopharyngeal carcinoma cells, where it downregulates the expression of epithelial cell markers and alters the expression of mesenchymal cell markers such as vimentin (VIM)." (PMID 38475805, 2024). "In line with this, CLDN1 overexpression associates with high grade OSCC perineural invasion and shown to upregulate EMT marker Vimentin in conjunction with nuclear translocation of β-catenin in nasopharyngeal carcinoma." (PMID 38942893, 2024). "Strong nuclear vimentin signals have also been found in lymph node metastasis from nasopharyngeal carcinoma." (PMID 26787680, 2016). "Nuclear transport and presence of IF proteins has been demonstrated for tail-less cytokeratin 8, 18, and 19 in 3T3 fibroblasts, for vimentin in nasopharyngeal carcinoma lymph node metastasis, for nestin in various brain tumors, and for desmin in BHK21 cells." (PMID 26787680, 2016). "Moreover, vimentin silencing in nasopharyngal cancer cells inhibits the expression of pro-angiogenic factors VEGF and CD31 as well as the formation of pulmonary metastasis in nude mice." (PMID 34203746, 2021). "A previous report showed that β-catenin might be a regulator of stem cell markers and could affect the expression of SOX2, c-MYC and vimentin in nasopharyngeal carcinoma cells." (PMID 33089188, 2020). "As a potential ligand of EGFR, EGFL6 could downregulate the expression of E-cadherin, upregulate the expression of F-actin and Vimentin, and promote metastasis of nasopharyngeal carcinoma through the EMT signal pathway." (PMID 32983976, 2020). "In nasopharyngeal carcinoma (NPC), the expression of YBX1 positively correlates with Vimentin expression, and TGF-β1 stimulation promotes YBX1 expression and EMT within CNE1 cells." (PMID 40346063, 2025). "PFKFB3 knockdown inhibits invasiveness by upregulating E-cadherin and downregulating vimentin and N-cadherin levels in CNE2 human nasopharyngeal carcinoma cells." (PMID 37919747, 2023). "SRGN is positively correlated with vimentin and negatively with E-cadherin, in HCC and nasopharyngeal carcinoma samples as well as in the nasopharyngeal carcinoma cell line CNE-2 and its highly metastatic clones." (PMID 36358747, 2022). "For example, VEGF enhances the expression of EMT markers N-cadherin, vimentin, and MMP2 and MMP9, reduces the expression of E-cadherin, promoting the invasion and migration of nasopharyngeal carcinoma cells." (PMID 35371324, 2022). "After treatment with MSC-exosomes, phosphorylated FGFR4 and ERK in nasopharyngeal carcinoma (NPC) cells increased, and the expression of EMT markers changed, presenting as down-regulation of E-cadherin, up-regulation of N-cadherin, and vimentin." (PMID 31357383, 2019). "The translocation of vimentin to the nuclei up on trabectedin treatment suggests that the tumors under treatment could select highly aggressive cells in keeping with previous reports in nasopharyngeal carcinoma where the nuclear vimentin expression correlates with lower survival." (PMID 29980789, 2018). "Accumulating evidence indicates that neoplastic spindle cells in nasopharyngeal carcinoma exhibit characteristic EMT features, characterized by significant E-cadherin downregulation concurrent with upregulated expression of β-catenin, vimentin, and other mesenchymal markers." (PMID 40458725, 2025). "In nasopharyngeal carcinoma cells, RKIP overexpression corresponded to the downregulation of Vimentin and other EMT biomarkers, while in RKIP knockdown experiments, vimentin is upregulated, showing a relationship between the expression of vimentin in response to RKIP." (PMID 36230521, 2022). "In addition, target genes, such as MMP-9, vimentin (VIM), and CDH1, which were found to be differently expressed in the nasopharyngeal carcinoma cells transfected with miR-10b mimics and with miR-10b inhibitors, were also involved in migration and invasion." (PMID 29262659, 2017).
nasopharyngeal carcinoma (continued). "In nasopharyngeal carcinoma (NPC) cells, hypoxic exosomes carry MMP-13, which significantly upregulates the expression of vimentin in recipient cells and reduces the level of E-cadherin, thereby promoting the EMT of NPC cells and enhancing their migratory and invasive abilities." (PMID 35359397, 2022). "Besides, in nasopharyngeal carcinoma (NPC), TGF-β could promote tumor invasion and EMT process by decrease of E-cadherin and increase of Vimentin, thus enhancing the resistance of cancer cells to irradiation." (PMID 35251963, 2022).
neuroblastoma (33 papers, 2008 to 2025). Neuroblastoma (NB) is the most common solid, extracranial childhood tumor. "Herein, we showed that c-Jun overexpression inhibited Vimentin expression, further supporting its role in neuroblastoma differentiation and transition from the ADRN to the MES phenotype." (PMID 40149013, 2025). "Since induction of neural differentiation markers BCL2 and NTRK2 was suppressed, we compared the expression of VIM, a characteristic marker of S-type neuroblastoma cells, in untreated wild-type and TOP2B null SH-SY5Y cells." (PMID 35831557, 2022). "In bulk transcriptomic and proteomic data, VIM was also highly expressed in neuroblastoma cells, which was in accordance with the IF staining results on neuroblastoma cell lines." (PMID 34503120, 2021). "A five-day RA-treatment upregulated vimentin expression in SH-SY5Y cells suggested that neuroblastoma cells start differentiating into neural progenitor cells." (PMID 33105690, 2020). "One of TRIM protein, TRIM16, has been demonstrated to acts as a tumour suppressor protein in neuroblastoma via effects on cytoplasmic vimentin and nuclear E2F1." (PMID 31342168, 2019). "Further, the downregulation of vimentin is required for the ability of TRIM16 to inhibit neuroblastoma cell migration." (PMID 31342168, 2019). "Decreased cellular proliferation and migration of neuroblastoma and squamous cell carcinoma cell lines by directly interacting with and reducing protein stability of cytoplasmic Vimentin and nuclear E2F1, respectively." (PMID 23404198, 2013). "Vimentin is, however, an essential transient requirement for the initiation of neurite outgrowth in NB2a neuroblastoma cells and also in hippocampal neurons where knockdown of vimentin significantly inhibited neurite outgrowth." (PMID 23220046, 2013). "Given that vimentin is a crucial regulator of the β1 integrin adhesive machinery, the observed downregulation of vimentin induced by leptin could explain its inhibitory effect on the adhesiveness of neuroblastoma cells." (PMID 37895840, 2023). "Therefore, vimentin is commonly seen in neuroblastoma and neural progenitor cells and was used to assess neuronal maturity as reflected in its reduced presence." (PMID 33105690, 2020). "Interestingly, the expression of neuronal vimentin by transfection of differentiated neuroblastoma cells with vimentin resulted in an enhanced axon outgrowth." (PMID 33240046, 2020). "In the context of a mimicking model for advanced neuroblastoma studies, we showed that cancer cells contained in bioprintable bioinks formed Homer Wright-like rosettes, maintained their proliferative capacities and produced Vimentin-rich matrices." (PMID 30764492, 2019). "The existence of such a species is supported by evidence of PrPSc and proteasome colocalisation in perinuclear aggresomes in prion-infected neuroblastoma cells and co-immunoprecipitation of PrPSc with vimentin and subunits of the 26S proteasome in prion-infected mouse brains." (PMID 26646779, 2016). "Upon validation, FAIM2, which was highly abundant by proteomics specifically in neuroblastoma cells, GD2, CD56, VIM and B7-H3 were selected for multiplex imaging of DTCs." (PMID 34503120, 2021). "TRIM16 exhibits tumour suppressor functions by interacting with cytoplasmic vimentin and nuclear E2F1 proteins in neuroblastoma and squamous cell carcinoma cells, reducing cell migration and replication." (PMID 23404198, 2013). "In addition to its predicted targeting of MYH9, miR-124-3p was predicted to target additional cytoskeletal genes (PLEC, ITGB1, VIM, and ACTN4) from our panel, which were overexpressed in the resistant SK-N-ASCis24 neuroblastoma cell model." (PMID 33330445, 2020). "The cytoskeletal genes MYH9, PLEC, ITGB1, VIM, and ACTN4, were previously reported by our lab to drive EMT-like morphological transformation and increased invasiveness (2.5 fold) in the MES SK-N-ASCis24 neuroblastoma cell line, coinciding with resistance development." (PMID 33330445, 2020).
neuroblastoma (continued). "These cytoskeletal genes (MYH9, PLEC, ITGB1) and mesenchymal markers (VIM, ACTN4), were previously reported by our lab to be up-regulated with cisplatin resistance development and involved in phenotypic and morphological modulation observed in our neuroblastoma cell model." (PMID 33330445, 2020). "Moreover, it has been found that SH-SY-5Y neuroblastoma cells do not express vimentin and that the selection with etoposide is able to stimulate vimentin which is basally expressed in HTLA cells." (PMID 27683112, 2016). "Here, neuroblastoma (NB) cell line subtypes were characterized according to embryonic peripheral nervous system development markers (GAP43, Phox2b, Sox10, c-kit, GD2, NF68, vimentin, S100β, calcyclin and ABCG2), morphological features, gene expression and differentiation potential." (PMID 19216736, 2009). "Substrate adherent, non-tumorigenic (S-type) neuroblastoma SHEP cells share many characteristics with Schwann cells, including tyrosinase activity specific for melanocytes and expression of fibronectin, vimentin, collagen IV, and SPARC." (PMID 27776337, 2016). "The lesion revealed positive immunoexpression for vimentin and CD99 and negative immunostaining for desmin, CD45, cytokeratin, and neuroblastoma protein, suggesting, then, the diagnosis of PNET." (PMID 22242031, 2011). "We assayed markers of both mesenchymal differentiation (VIM, PRRX1 and SNAI1) and adrenergic differentiation (NCAM, NF68), but observed no reproducible changes in gene expression, suggesting that GATA3 knock-down only affects proliferation and death, but not differentiation, in neuroblastoma cells." (PMID 31831790, 2019).
metastatic carcinoma (31 papers, 2008 to 2025). A carcinoma which has spread from the original site of growth to another anatomic site. "Vimentin expression is associated with aggressive and metastatic cancers." (PMID 37833712, 2023). "Because Vimentin is associated with the mesenchymal phenotype of aggressive cancer cells in metastatic cancer progression, we first investigated whether RNF208 regulates the expression of EMT markers in Hs578T and MDA-MB-231 cells." (PMID 31862882, 2019). "Our findings indicate that metastatic cancers exploit the buffering function of vimentin to increase surface integrin β1 levels, thereby enhancing cell survival in suspension." (PMID 38915055, 2024). "Metastatic cancer-1 cells highly expressed mesenchymal markers (e.g., VIM, FN1, and COL1A1), typical of EMT, whereas metastatic cancer-2 cells highly expressed partial EMT (p-EMT) signature genes (e.g., LAMC2, PDPN, and INHBA), indicative of a p-EMT phenotype." (PMID 37853464, 2023). "Vimentin is highly expressed in metastatic cancers, and its expression correlates with poor patient prognoses." (PMID 37161053, 2023). "In advanced metastatic cancers with reduced patient survival and poor prognosis, expression of vimentin, a type III intermediate filament protein is frequently observed." (PMID 36552797, 2022). "The finding that vimentin is targeted and disrupted by ajoene supports the dietary role of ajoene in the protection and control of metastatic cancer." (PMID 30894168, 2019). "Taken together, the findings support the role of ajoene as a natural dietary phytochemical able to offer protection against metastatic cancer, mediated through binding to the vimentin target." (PMID 30894168, 2019). "Metastatic cancer (group II) exhibited the highest N-cadherin and vimentin expression, and the lowest E-cadherin expression." (PMID 26702618, 2015). "Elevated expression of miR-200c-3p and miR-200b-3p, resulting in reduced vimentin levels, is therefore expected in metastatic cancer, where epithelial features are important for re-colonization, in concordance with our findings." (PMID 24512620, 2014). "Downregulation of E-cadherin and upregulation of mesenchymal markers (α-SMA, vimentin and twist) are some of the most frequently reported phenomena in metastatic cancers." (PMID 19002171, 2008). "Vimentin nuclear translocation and overexpressed P62 of cancer cells may be used to predict patient prognosis, and targeting vimentin nuclear translocation may be a promising therapeutic strategy for metastatic cancers." (PMID 37833712, 2023). "Snail and Slug (zinc finger proteins) are direct transcriptional factors that enhance the EMT pathway in highly invasive and metastatic cancer; thus, we examined the expression of these two upstream transcription factors and a downstream mesenchymal marker (vimentin) in relation to miR-139 in BCSCs." (PMID 34070538, 2021). "Dynamics and function of vimentin as a decisive element of the cell cytoskeleton in migrating cells are responsible for the process of cell migration and for the invasive behaviors of metastatic cancer cells by altering microtubules and actomyosin networks." (PMID 34323425, 2021). "Targeting nuclear vimentin may be a promising therapeutic strategy against metastatic cancers." (PMID 37833712, 2023). "Surface vimentin expression may be a common marker for various metastatic cancers." (PMID 24212937, 2011). "Results revealed a higher Mesenchymal markers in primary cancer cells (e.g., NCAM1, LAMB1, SERPINE1, TCF4, VIM, ZEB1, and ZEB2) and a higher Epithelial markers in metastatic cancer cells (e.g., CDH1, CLDN4, ELF3, EPCAM, KRT18, KRT7, and KRT8)." (PMID 37202394, 2023). "The protein expression of vimentin and ZEB, regulators of EMT, were significantly decreased in metastatic cancer." (PMID 29137327, 2017).
metastatic carcinoma (continued). "Losses of expression of epithelial adherens junction protein (E-cadherin) with a concomitant gain of mesenchymal marker expression (vimentin) are distinctive events in EMT and are common in metastatic carcinomas." (PMID 26517117, 2015). "Finally, determining the actual topography of what domains of vimentin are expressed on the surface of prostate and other metastatic cancer cells could provide insights for the creation of novel therapeutic antibody agents, such as spectral-targeted antibody derivative constructs." (PMID 24212937, 2011). "The expression levels of SLC7A11 and vimentin were higher in cancer tissues compared with normal tissues, especially the IRSs of SLC7A11 and vimentin were higher in metastatic cancer tissues than in non-metastatic cancer tissues." (PMID 39543094, 2024). "Furthermore, in metastatic cancer, epithelial cancer cells experience EMT concomitant with upregulation of vimentin as they disassociate from primary tumors, transform into mesenchyme, and migrate." (PMID 21347296, 2011). "The expression of cytokeratin and transthyretin by tumor cells and the lack of GFAP expression differentiated this tumor from ependymoma, and the co-expression of cytokeratin, S-100 protein and vimentin with negative CEA was helpful in distinguishing it from metastatic carcinoma." (PMID 22752623, 2013). "Although absent in normal epithelial cells, vimentin expression is upregulated during oncogenic transformation and is considered a hallmark of the epithelial–mesenchymal transition (EMT) in motile epithelial cells during embryonic development and in metastatic cancer cells." (PMID 35122388, 2022). "In both carcinomas in situ and metastatic carcinomas, we observed that Meis1-EGFP was co-expressed with the epithelial basal marker K14, but not with the mesenchymal marker vimentin." (PMID 25013928, 2014).